TAF11L7 (TATA-box binding protein associated factor 11 like 7)
Tractability: No criterion of Open Targets' tractability assessment is met for any kind of drug.
Gene: Protein-coding gene on chromosome 5 (17,585,162 to 17,585,758, reverse strand). Ensembl gene ENSG00000284465.
Gene Ontology:
Molecular function: RNA polymerase II general transcription initiation factor activity; protein heterodimerization activity
Biological process: RNA polymerase II preinitiation complex assembly; transcription initiation at RNA polymerase II promoter
Cellular component: transcription factor TFIID complex; nucleus
Homologues: Orthologues: tropical clawed frog taf11 (45% identical), zebrafish taf11 (45% identical), Drosophila melanogaster Taf11 (42% identical), Caenorhabditis elegans taf-11.1 (33% identical), Caenorhabditis elegans taf-11.2 (27% identical). Paralogues in human: TAF11L10 (100% identical), TAF11L5 (100% identical), TAF11L6 (100% identical), TAF11L8 (100% identical), TAF11L3 (99% identical), TAF11L4 (99% identical), TAF11L9 (99% identical), TAF11L13 (95% identical), TAF11L2 (92% identical), LINC02218 (88% identical), TAF11L12 (87% identical), TAF11L11 (85% identical), and 2 more.